CD4 (CD4 molecule)
Diseases named in the same sentence as CD4 in open-access papers (continued):
Sharing a sentence is not in itself a finding about the gene and the disease.
tumor (continued). "Infiltrating CD4+ T cells and CD8+ T cells within malignancies are known to limit tumor activity, whereas Tregs are more likely to promote tumor growth." (PMID 36311770, 2022). "We next found significant enrichment of convergent TCR clusters in PD1+CD39+ subpopulations of both CD4+ and CD8+ TILs, which were previously shown to be enriched in terms of tumor reactivity." (PMID 35377314, 2022). "The higher expression levels of these antigens were not only significantly associated with the poorer prognosis of COAD, but also positively correlated with higher levels of tumor infiltrating B cells, CD8+ T cells, CD4+ T cells, and APCs." (PMID 35593226, 2022). "More recently, we reported the presence of a subset of CD4 Th cells that co-express PD-1 and ICOS, a phenotype reminiscent of Tfh cells, in the tumor microenvironment (TME) of HNSCC tumors." (PMID 35937775, 2022). "The combination of anti-PD-1 inhibitory and anti-OX40 agonist antibodies reduces the proportion of T-regulatory and exhausted T cells in PDAC and increases numbers of memory CD4+ and CD8+ T cells, eradicating all detectable tumor." (PMID 35965504, 2022). "Regulatory T cells (Tregs) are CD4+ CD25+ T cell subsets and are believed to promote tumor development mainly through immunosuppression." (PMID 36611857, 2022). "Like CD4+ Treg cells, both of these CD8+ and γδ-TCR Treg cell subtypes have immune suppression ability and inhibit anti-tumor immunity." (PMID 35309296, 2022). "In conclusion, we have shown that among the CD4+ Th TILs, cells coexpressing PD-1 and ICOS were enriched for tumor reactivity." (PMID 35439168, 2022). "Tregs are an immunosuppressive subset of CD4+ T cells characteristically expressing CD4, CD25, and FOXP3, and exhibit diversity and functional heterogeneity across tumor types." (PMID 36532071, 2022). "Cluster 2 exhibited an immune-inflamed phenotype, with high levels of CD4+ T cells and CD8+ T cells in the tumor parenchyma." (PMID 35892841, 2022). "For the immune cell fraction in the leukocytes of the tumor tissues (TILs), the main population comprised CD8+ T, CD4+ T, Mo/Mφ, and B cells." (PMID 35577913, 2022). "Studies have shown that the infiltration and metastasis of immune cells, memory CD4+ T cells, and CD8+ T cells in the TME can regulate tumor immunity and participate in the three stages of tumor cell clearance, tumor and body balance, and tumor immune escape." (PMID 36389763, 2022). "As our interest was in defining tumor antigen-reactive TCR clonotypes, we evaluated CDR3 Vβ sequences recovered by TCR-seq from sorted CD8+ (total n=1695) and CD4+ (total n=1755) T cells from PBMC expanded with neoantigen-specific peptide." (PMID 35361728, 2022). "The proportion of all tumor-infiltrating lymphocytes was significantly elevated in the FCGRT high group, except for activated CD4+ T cells and type 2 T helper cells." (PMID 36339597, 2022). "Based on our findings, the proportions of anti-tumor immune cells, including CD8+ T cells, CD4+ memory activated T cells, and follicular helper T cells, were significantly increased in the low-risk group compared with the high-risk group." (PMID 35912252, 2022). "Administration of DCs transduced for production of IL-12 alone and in combination with IL-18 increased the inflow and activity of CD4+ and CD8+ T lymphocytes in the tumor microenvironment and tumor-draining lymph nodes." (PMID 35372586, 2022). "Interestingly, in patients with pancreatic cancer, tumors with tertiary lymphoid structures were less enriched for tumor-infiltrating CD103+ cells, suggesting that the biology driving expansion of CD4 Tfh in tumor follicular structures may be different from that driving Trm." (PMID 35937775, 2022). "DC capture tumor antigens and present them through HLA class II or I molecules to CD4+ Tn or CD8+ Tn that can differentiate into Th and memory CD4+ T cells or memory CD8+ T cells, also known as the initial immune response." (PMID 36119064, 2022).
tumor (continued). "We did not observe a significant difference in lymphoid cell recruitment in Tlr2−/− tumor-bearing lungs via flow cytometry analysis, and this was confirmed using IHC staining for the T cell markers CD3, CD4, and CD8." (PMID 36351380, 2022). "TIM-3 is a negative regulator of T-cell function expressed on the surface of CD4+ helper T cells and CD8+ cytotoxic T cells and has been shown to promote T-cell depletion during tumor progression and chronic viral infections." (PMID 35559250, 2022). "Pro-inflammatory macrophages and MDSC are first recruited into the tumor by CCL2, which is followed by the infiltration of CD8+ effector and CD4+ helper T cells and eventually accumulation of regulatory T cells." (PMID 35856032, 2022). "Finally, to determine whether the combination of double or triple regiment impacts immune cell infiltration within the TME, we analyzed the defense presented by CD8+ and CD4+ T cells, immunosuppressive cells such as Tregs, and CD11b+ myeloid cells in the tumor-bearing mice." (PMID 35058524, 2022). "Tregs are able of suppressing tumor-specific effector cells, such as lymphocytes CD8+, CD4+ and Natural Killer cells." (PMID 36068484, 2022). "In vivo, the combination treatment not only reduced the tumor proliferation stronger than the controls, but also increased a high level of CD8+ and CD4+ T cells infiltration." (PMID 36329529, 2022). "Given the importance of CD4 T-cell help for CD8 T-cell proliferation, both at the tumor site and in the periphery, here, we investigated the expression of PD-1 and CD39 in circulating CD4 T cells in cancer patients bearing HPV-induced malignancies." (PMID 35954341, 2022). "In tumor microenvironments, the cells supporting cancer cells, such as CAF, CD4+ T cells, Treg, MDSC, and TAM, inhibit the epithelial state of tumor, promote and activate the mesenchymal state." (PMID 35685630, 2022). "Tumor antagonistic immune cells are mainly composed of effector T cells (CD8+ T and CD4+ T cells), NK cells, DCs, M1-type macrophages, and N1-polarized neutrophils." (PMID 36090985, 2022). "In contrast, anti-PD-L1-bound platelets are activated in the tumour microenvironment and release anti-PD-L1-bound EVs, which inhibit immune checkpoints in tumour tissue, thereby increasing the number of infiltrating CD8+ and CD4+ T cells within the tumour." (PMID 36298556, 2022). "We depleted CD8+ T cells, CD4+ T cells, or NK cells before inoculation with KPC tumor cells and combined antibody treatment to determine which immune cell types are critical for the effects of the combination therapy." (PMID 35260434, 2022). "Depletion of CD4+ or CD8+ T cells were performed using anti-CD4 or anti-CD8 monoclonal antibody injection i.p. one day before and four days after tumor rechallenge, respectively." (PMID 35874660, 2022). "The antitumor effect was investigated by eliminating CD4+ or CD8+ T cells in mice, and it was found that CD8+ cell depletion significantly accelerated tumor growth, which indicated that αFAP-Z@FRT elicited tumor-specific T-cell immune responses." (PMID 35566065, 2022). "In a murine model of lung adenocarcinoma, B cells were found to promote tumor-specific CD4+Tfh cell differentiation, which then produced IL-21 to enhance CD8+T cell responses to drive anti-tumor immunity." (PMID 36465392, 2022). "These immunological agents are then secreted from the cells to facilitate the infiltration of anti-tumor CD4+ and CD8+ T cells into the tumor microenvironment, leading to enhanced anti-tumor immunity and response to immune checkpoint blockade." (PMID 36362142, 2022). "While CD20+ B cells are present throughout the tumor, CD4+ cells accumulate in the peritumor area and CD8+ T cells on the tumor front." (PMID 39301518, 2022). "Tumor-derived exosomes and CCL20 facilitate Treg recruitment as well as conventional CD4(+)CD25(−) T cells, which are converted into inhibitory CD4(+) CD25 (high) cells." (PMID 36233088, 2022).
tumor (continued). "Tumor hypoxia results in expression of CCL28, which promotes the recruitment of CD4+CD25+FOXP3+ Treg cells by binding to the corresponding receptor, CCR10, on Treg cells." (PMID 35759090, 2022). "In a tumour-immune context, CD39 expression on activated CD4+ T-cells is indicative of exhausted T-cells that carry out effector functions, where CD39 contributes to T-cell attrition and clonal contraction of CD4+ T-cells." (PMID 35158816, 2022). "In the locally advanced NSCLC, the proportion of tumor cells and CAFs in IM is lower than in the TC, while MVD, CD4+, and CD8+ T lymphocytes were increased, and tumor cells were closer to T lymphocytes and their subsets." (PMID 36685566, 2022). "The proliferation of CD4+CD25+ Treg cells can be stimulated by inhibitory cytokines, such as IL-10 and TGF-β secreted from tumor cells within the TME, and they directly inhibit the activation of CD8+ effector T cells and restrict their IL-2 production." (PMID 36553542, 2022). "Evaluation of the proliferative index Ki67 confirmed an increased proliferative activity of both CD4+ Th and CD8+ T-cells only in “Large tumor” group that correlates with NADPH assay." (PMID 36555468, 2022). "Using enzymatic double-staining immunohistochemistry, we analysed CD8 + PD-1+ TILs and CD4 + FoxP3+ TIL counts in the stroma and intra-tumour in nine ICC patients selected based on high TILs in hematoxylin and eosin staining." (PMID 35597869, 2022). "The baseline levels of tumor-infiltrating CD8+ T cells, CD4+ T cells, and NK cells are related to the likelihood of an immune response." (PMID 35875124, 2022). "TIM-3, which is expressed on the surface of CD4+ and CD8+ T cells, is involved in enforcing T-cell exhaustion by interaction with tumour cells; therefore, TIM-3 is considered as an exhaustion marker of lymphocytes similar to programmed cell death 1 (PD-1)." (PMID 35597869, 2022). "Previous studies demonstrated that CD4+ T cells can uptake tumor antigen-pulsed dendritic cell-derived exosomes (DEXO), which harbor tumor antigen peptide/pMHC I complex and costimulatory molecules and show potent effects on inducing antitumor immunity." (PMID 36466863, 2022). "Some types of infiltrating immune cells have anti-tumor activities, such as CD8+ cytotoxic T lymphocytes (CTL), CD4+ T helper cells, natural killer cells, and dendritic cells." (PMID 35795206, 2022). "GI-6301, which delivers antigens through dendritic cells, specifically activates CD4+ and CD8+ cell and has a lethal effect on brachyury-expressing tumor cells." (PMID 36185236, 2022). "MDSCs, TAMs, and Tregs promote tumor progression, whereas CD4+ T-cells, CD8+ T-cells, NK cells, and dendritic cells promote tumor destruction." (PMID 35873573, 2022). "Simultaneously, they secrete relevant cytokines as immune helper cells to recruit, stimulate, and regulate DCs, CD4+ T cells, and CD8+ T cells to further activate the anti-tumor immune response." (PMID 36072581, 2022). "FH produced by the DCs in the TME inhibits the proliferation of CD4+ T cells, thereby creates an immunosuppressive TME that enhance the tumor progression and radiotherapy-resistance." (PMID 36338737, 2022). "Next, we detected the CD4+ and CD8+ T cell subsets, as well as the dendritic cell marker CD11c and regulatory T cell (Treg) marker FoxP3 expression in spleen tissues and tumor tissues by immunohistochemistry." (PMID 36238646, 2022). "Both CD4+ and CD8+ T cells per 105 splenocytes decreased in 4T1 tumor-bearing mice, whereas total splenic CD4+ T cells were unchanged." (PMID 36232335, 2022). "This multifunctional strategy upregulated the maturation of DCs, increased the secretion levels of TNF-α and IFN-γ, promoted the Th1 immune response, and increased tumor T-cell infiltration with proper CD8+ CTLs/Tregs and effector CD4+ T cells/Tregs ratios." (PMID 35335881, 2022).
tumor (continued). "It has been reported that Ccl5 can induce the infiltration of CD8+ T cells 55, CD4+ T cells 56, and NK cells 31 into the TME, thereby enhancing the anti-tumor immune responses." (PMID 36438484, 2022). "We found that most transferred tumor-specific CD4+ T cells converted to Th1 cells and some of them gradually lost CD4 expression and differentiate into CD4– T cells, which is consistent with previous report that upon chronic antigen exposure, helper T cells could down-regulate CD4 expression." (PMID 35784297, 2022). "The prior study indicated that the reduction of a tumor-infiltrating neutrophil by CD11b agonist resulted in an increase in the number of CD8+ and CD4+ T cells." (PMID 36246355, 2022). "As with cancer vaccines, CD4+ and CD8+ T cells travel to the tumor site and, upon finding corresponding antigens, kill tumor cells by cytotoxicity and cytokine production." (PMID 36558778, 2022). "Among these, the immune-hot clusters were characterized by abundant adaptive immune cell infiltration, active CD4+ and CD8+ T cells, high total leukocyte counts and tumor growth status, and lower Th17 cell and M2 macrophage densities." (PMID 35053610, 2022). "Older DLBCL also manifested reduction in CD4+ naïve T and CD8+ naïve T cells, and also increased recruitment of exhausted T cells and macrophages, leading to immunosuppressive tumor microenvironment." (PMID 35401516, 2022). "The presence of B cells, CD4+, CD8+ T cells, and DCs in the G4 tumor presumably characterize the TLS." (PMID 35563678, 2022). "To clarify how Activin-A promotes immune escape, we depleted CD8+ or CD4+ T cells in βΑ and Ctrl B16.OVA tumor-bearing mice." (PMID 35580932, 2022). "Although the CD4+ T cells were dispensable for pIL-12 GET combination therapeutic efficacy, we found that the combination anti-tumor effect predominantly relied on CD8+ T cells." (PMID 36365247, 2022). "As the disease progresses to HGCIN and SCC, increased synthesis of HLA-DRA protein recruits immune support via CD4+ T cells, leading to more favourable CD8+ T-cells responses and thus preventing tumour invasion." (PMID 35208514, 2022). "In contrast, AN3025 treatment increased CD4+ T cells and CD8+ T cells infiltration to a greater extend, suggesting another potent anti-tumor mechanism." (PMID 35251028, 2022). "It is clear that there are abnormal ratios of CD4+ and CD8+ cells within the tumour microenvironment." (PMID 35158816, 2022). "In contrast, Treg cells function as immune suppressors by inhibiting the activation of both CD4+ and CD8+ T cells, are generally found in higher numbers in tumor microenvironments, and secrete cytokines such as transforming growth factor-beta-1 (TGF-β1)." (PMID 36005179, 2022). "Remarkably, the abundance of TIICs, including CD8+, CD4+, CD68+, CD20+ and CD66b+ cells, significantly increased with the increase in CPS, indicating a ‘hotter’ tumour immune environment." (PMID 35982052, 2022). "Strikingly, Smad4KO‐mediated tumor suppression was totally abolished after CD8+ cells were depleted and partially attenuated when CD4+ cells were depleted." (PMID 35064757, 2022). "CXCR3 is known to be expressed by both Th1 CD4+ T-cells and CD8+ effector T-cells and plays an important role in T-cell homing to the tumor site." (PMID 36230815, 2022). "Conversely, a significant increase in the frequencies of T lymphocytes, CD4+T lymphocytes, and CD4+ and CD8+ T lymphocytes expressing PD1 and CD39 was evident in tumor tissue in comparison with the healthy breast tissue." (PMID 35051220, 2022). "Anti-PD-1 antibody monotherapy slightly increased CD4+ T cells and CD8+ T cells infiltration in our MC38 tumor model, which is consistent with a previous report." (PMID 35251028, 2022). "Mice receiving anti-IFNAR1 antibody showed a significant increase in PD-1 expressing tumor-infiltrated CD4+ and CD8+ T cells and a significant increase in tumor-infiltrating M2-like macrophages (CD206+ F4/80+), compared to the isotype control treated group." (PMID 36311701, 2022).
tumor (continued). "Clearly, depletion of CD4+ T cells or CD8+ T cells abolished the antitumor effect induced by cryo-thermal therapy, leading to tumor growth in the lung." (PMID 35874660, 2022). "For further confirmation of our TME flow cytometry data showing CD4 and CD8 T-cell activation, we found an increase in Th1 pro-inflammatory cytokine (IFNγ, TNFα, IL-2, and KC/GRO) levels in the tumor lysate." (PMID 35651802, 2022). "Tregs exert significant effects on inhibiting the function of IFN-γ-expressing CD4+ Th1 cells and producing the secretion of VEGF through hypoxia-mediated CCL-28, which both strikingly result in a pro-angiogenic tumor microenvironment." (PMID 36439137, 2022). "CD4 and CD8 expression on the tumor (tCD4/CD8), stroma (sCD4/CD8), and invasive front (iCD4/CD8) was evaluated." (PMID 36428666, 2022). "It has been reported that human B cells can efficiently present peptides to CD4+ T cells after being activated by CD40 ligand and pulsed with tumor antigen." (PMID 35967441, 2022). "These phenotypical changes were also associated with enhanced IL-15-mediated cytotoxicity against different tumor cell lines and HIV-infected CD4 T cells." (PMID 35867565, 2022). "In matched parental tumor and PDOs pairs (ccRCC-07 and ccRCC-08), the composition and subsets of CD8+ T cells, CD4+ T cells were mostly maintained." (PMID 36544542, 2022). "This novel CD4-IL15/IL15sushi CAR then demonstrated potent in vitro and in vivo anti-tumor efficacy in multiple CD4+ cell lines, confirming that the addition of the IL15/IL15sushi complex enhanced anti-tumor targeting and killing." (PMID 36172388, 2022). "(C) IFN-γ, and CD44 expression of CD4+ and CD8+ tumor-infiltrating lymphocytes (TILs) in tumor-bearing mice." (PMID 36426850, 2022). "The immune infiltration, vascularization, and viral presence in the tumor were determined by CD3, CD4, CD20, CD31 and CAV by immunohistochemistry." (PMID 35878344, 2022). "In the peripheral blood and tumor tissues of patients with EBV-positive tumors, an increasing number of natural CD4+CD25+ regulatory T cells (Tregs) have been found." (PMID 35632758, 2022). "In this study, we found that the more UV-induced damage observed in the skin near the tumour, the less CD3+, CD4+ and CD8+ TILs were identified." (PMID 35365704, 2022). "During this time, the percentage of CD4+ and CD8+ cells with proliferative capacity (KI67+) clearly decrease in the tumor microenvironment." (PMID 35626103, 2022). "Spatial analysis of the TME will be necessary to confirm the cellular interactions of CD4 Tfh and CD8 in human tumor specimens." (PMID 35937775, 2022). "Comprehensive immune profiling showed that L. lactis GEN3013 augmented cytotoxic immune cell populations, such as CD4+ T cells, CD8+ effector T cells, and NK cells in the tumor microenvironment." (PMID 36077619, 2022). "Further analysis of the tumor immune environment revealed that the C_1 cluster was enriched in activated CD8 T cells and effector CD4 T cells, whereas the C_2 cluster was enriched in eosinophils, mast cells and DC cells and, thus, in immunosuppressive cells." (PMID 35834099, 2022). "In tumors that do not express MHC-II, the participation of CD4+ T-cells in the local immune response relies on resident professional APCs that take up tumor cells and present their processed antigens on MHC-II to infiltrating CD4+ T helper cells." (PMID 35655709, 2022). "Similar to that observed in the spleen, p40 mAb treatment also upregulated human CD4+CD8+, CD4+IFNγ+ and CD8+IFNγ+ T cells in tumor tissues of PDX mice." (PMID 35053375, 2022). "B7-H4 inhibits the proliferation, cell cycle progression and cytokine production of CD4+/CD8+ T cells, attenuates the inflammatory response, and enables tumor cells to evade the immune system." (PMID 36561746, 2022).